TRBV20-1 (T cell receptor beta variable 20-1)
Description:
V region of the variable domain of T cell receptor (TR) beta chain that participates in the antigen recognition. Alpha-beta T cell receptors are antigen specific receptors which are essential to the immune response and are present on the cell surface of T lymphocytes. Recognize peptide-major histocompatibility (MH) (pMH) complexes that are displayed by antigen presenting cells (APC), a prerequisite for efficient T cell adaptive immunity against pathogens. Binding of alpha-beta TR to pMH complex initiates TR-CD3 clustering on the cell surface and intracellular activation of LCK that phosphorylates the ITAM motifs of CD3G, CD3D, CD3E and CD247 enabling the recruitment of ZAP70. In turn ZAP70 phosphorylates LAT, which recruits numerous signaling molecules to form the LAT signalosome. The LAT signalosome propagates signal branching to three major signaling pathways, the calcium, the mitogen-activated protein kinase (MAPK) kinase and the nuclear factor NF-kappa-B (NF-kB) pathways, leading to the mobilization of transcription factors that are critical for gene expression and essential for T cell growth and differentiation. The T cell repertoire is generated in the thymus, by V-(D)-J rearrangement. This repertoire is then shaped by intrathymic selection events to generate a peripheral T cell pool of self-MH restricted, non-autoaggressive T cells. Post-thymic interaction of alpha-beta TR with the pMH complexes shapes TR structural and functional avidity.
Synonyms: TRBV201; TCRBV20S1; TCRBV2S1
Gene: T-cell receptor variable (V) gene on chromosome 7 (142,626,649 to 142,627,399, forward strand). Ensembl gene ENSG00000211747.
Subcellular location: Cell membrane
Gene Ontology:
Biological process: cell surface receptor signaling pathway
Cellular component: plasma membrane
Homologues: Orthologues: mouse Trbv20 (53% identical). Paralogues in human: TRBV20OR9-2 (89% identical), TRBV29-1 (59% identical), TRBV6-1 (30% identical), TRBV6-2 (29% identical), TRBV6-5 (29% identical), TRBV4-2 (28% identical), TRBV6-8 (28% identical), TRBV12-5 (27% identical), TRBV19 (27% identical), TRBV6-4 (27% identical), TRBV6-7 (27% identical), TRBV10-1 (26% identical), and 39 more.
Diseases named in the same sentence as TRBV20-1 in open-access papers:
TRBV20-1 is named in the same sentence as 12 diseases in open-access papers, as found by Europe PMC text mining. Sharing a sentence is not in itself a finding about the gene and the disease. The quoted sentences say what the papers report.
lung carcinoma (2 papers, 2021 to 2022). "Furthermore, TRBV20-1 usage has been associated with improved response and survival in lung cancer patients treated with anti-PD1 therapy such as Durvalumab." (PMID 35559031, 2022). "Additionally, among the 9 VJ gene usages identified in lung cancer patients treated with Durvalumab, one of the identified V segments, TRBV20-1 has been previously shown to be differentially expressed in cancer tissue compared to healthy tissue." (PMID 35559031, 2022).
pleural tuberculosis (2 papers, 2024 to 2025). Inflammation of the pleura secondary to an infection with Mycobacterium tuberculosis. "Notably, TRBV20-1 plays a crucial role in the proliferation of pleural effusion monocytes (PEMCs) and exhibits high expression in TCRs in pleural tuberculosis, suggesting that TRBV20-1 may be a prevalent TCR clonotype in TB patients." (PMID 40092995, 2025). "Another study used the high-throughput deep sequencing methods to analyze the TCRB repertoires of an untreated pleural tuberculosis patient, and the results indicated that the TRBV20-1 family and TRBV20-1/TRBJ1-5 gene combination had a dominant expression in PEMCs, but not in PBMCs of the patient." (PMID 39664375, 2024).
autoimmune disease (1 paper, 2025). A disorder resulting from loss of function or tissue destruction of an organ or multiple organs, arising from humoral or cellular immune responses of the individual to their own tissue constituents. "TRBV20‐1 has been linked to autoimmune diseases and viral infections, suggesting that its preferential use may be related to the pathogenesis of MS." (PMID 40583051, 2025).
contact dermatitis (1 paper, 2021). An inflammatory skin condition caused by direct contact between the skin and either an irritating substance or an allergen. "In this study, we showed several highly expanded T cell clones by sequencing data, and demonstrated the preferential usage of TRBV19, TRBV5-1, and TRBV20-1, consistent with previous studies on Ni2+ contact dermatitis." (PMID 33670995, 2021).
HIV-1 infection (1 paper, 2020). The type species of lentivirus and the etiologic agent of acquired immunodeficiency syndrome (AIDS). "The diversifying effect of acute HIV-1 infection was also associated with the contraction of the dominant α and β chain clones pre-infection, and specifically of TRBV20–1 (Vβ2) usage, in the MAIT cell repertoire." (PMID 31937782, 2020).
rheumatoid arthritis (1 paper, 2023). A chronic, systemic autoimmune disorder characterized by inflammation in the synovial membranes and articular surfaces. "Interestingly, a recent study also reported preferential usage of the TRBV20-1 gene by citrulline specific T cell clones in rheumatoid arthritis synovial fluid, a phenomenon which was not seen in influenza-specific T cell clones." (PMID 38268914, 2023).
tumor (3 papers, 2021 to 2023). "In line with our results, TRBV20-1 has been reported previously as one of the most used V-gene in tumor-infiltrating T lymphocytes in several solid tumors." (PMID 34204662, 2021). "Remarkable expansions of TRBV20-1 and TRBJ2-5 co-occurred in both MPR patients (P16 and P18) but not in other patients, suggesting that TRBV20-1 and TRBJ2-5 might contribute to anti-tumor immunity." (PMID 36596787, 2023).
cancer (2 papers, 2019 to 2022). A tumor composed of atypical neoplastic, often pleomorphic cells that invade other tissues. "We also compared the TRBV and TRBJ gene usage frequency between cancer tissues and normal lung tissues and found that TRBV20-1 and TRBV18 were used more frequently in cancer tissues than in normal lung tissues." (PMID 31479759, 2019). "In our study, TRBV20-1 and TRBV18 were identified as differentially enriched gene segments between cancer tissues and normal lung tissues." (PMID 31479759, 2019).
TRBV20-1 also shares sentences with these, for which no sentence is quoted: infection (1 paper); Pleural effusion (1); tuberculosis (1); viral infections (1).